RFC1 (replication factor C subunit 1)
Diseases named in the same sentence as RFC1 in open-access papers (continued):
Sharing a sentence is not in itself a finding about the gene and the disease.
neuropathy (continued). "Very recently, RFC1 expansions were found in patients with Sjögren syndrome who had neuropathy that did not respond to immunotherapy." (PMID 37853169, 2023). "The RFC1 AAGGG repeat expansion was common in patients with pure sensory neuropathy (21/40, 53%) and less frequent in cases with predominantly sensory (10/56, 18%, P < 0.001) or sensorimotor (3/138, 2%, P < 0.001) neuropathy." (PMID 33884451, 2021). "Very recently, RFC1 expansions were found in patients with Sjögren syndrome who had neuropathy that did not respond to immunotherapy, suggesting that neuropathy could be attributed to RFC1 expansions." (PMID 37853169, 2023). "Of note, these criteria were developed and then validated in a cohort in which only 5% of patients had inherited neuropathy, and none had CANVAS/RFC1‐neuropathy." (PMID 41063615, 2026).
Sensory neuropathy (23 papers, 2020 to 2026). Peripheral neuropathy affecting the sensory nerves. "CANVAS results from a biallelic, nonreference, pentameric CCCTT(AAGGG) repeat expansion in the second intron of replication factor complex subunit 1 (RFC1) and this same expansion also causes late-onset idiopathic ataxia and sensory neuropathy in isolation." (PMID 39231235, 2024). "Biallelic RFC1 repeat expansions were shown to represent a common cause of late onset ataxia and sensory neuropathy, explaining 22% and 34% of genetically unconfirmed cases, respectively." (PMID 37892228, 2023). "We identified RFC1 AAGGG biallelic expansions in 34% of patients with sensory CIAP suggesting that RFC1 expansions represent a significant genetic cause of sporadic sensory neuropathy." (PMID 33969391, 2021). "Biallelic RFC1 expansions represent a common cause of late-onset ataxia and sensory neuropathy." (PMID 37892228, 2023). "Therefore, exactly how an intronic biallelic repeat expansion in the RFC1 gene leads to a sensory neuropathy, later associated with vestibular and cerebellar dysfunction, remains unclear." (PMID 33983437, 2021). "Two per cent of 138 patients with sensorimotor, 18% of 56 patients with sensory predominant and 53% of 40 patients with pure sensory neuropathy had bi-allelic RFC1 repeat expansions." (PMID 41322202, 2025). "Sensory neuropathy was present in all patients tested, confirming the central role of sensory involvement in RFC1 disease." (PMID 38193360, 2024). "Forty-two per cent of RFC1-positive patients had isolated sensory neuropathy or sensory neuropathy with chronic cough, while vestibular and/or cerebellar involvement, often subclinical, were identified at examination in 58%." (PMID 33969391, 2021). "Of all features, chronic cough, sensory ataxia with use of visual control, sensory neuropathy symptoms, and axonal sensory neuropathy yield the highest predictive values to discriminate RFC1-positive (n = 70) from RFC1-negative (n = 24) patients." (PMID 33495376, 2021). "Here we describe the full spectrum of the disease phenotype in our first 100 genetically confirmed carriers of biallelic repeat expansions in RFC1 and identify the sensory neuropathy as a common feature in all cases to date." (PMID 32040566, 2020). "Testing for the RFC1 repeat expansion should be considered in all cases with the full CANVAS phenotype as well as in cases with sensory neuropathy, particularly, but not only, if cerebellar, vestibular involvement and/or unexplained chronic cough coexist." (PMID 32040566, 2020). "In fact, all our patients presented with sensory axonal neuropathy, and it is well established that RFC1‐related diseases are characterized by severe and widespread sensory neuropathy also affecting small nerve fibers, that have been implied in the pathogenesis of RLS." (PMID 40879541, 2025). "Given that sensory neuropathy may present as the original or predominant phenotype of RFC1/NOTCH2NLC-related disorders, we screened these non-coding repeat expansions in a Japanese case series with HSAN." (PMID 36061987, 2022). "Notably, a sensory neuropathy/neuronopathy has been present in all the patients with biallelic RFC1 expansions to date and can be observed as an isolated complaint in some, possibly reflecting an early stage of this complex neurological disease." (PMID 33969391, 2021). "Of 125 patients with sensory neuropathy 43 (34%) carried biallelic AAGGG repeat expansions in RFC1." (PMID 33969391, 2021). "Therefore, we speculated that biallelic RFC1 expansions could account for a proportion of idiopathic sensory neuropathies also diagnosed as CIAP." (PMID 33969391, 2021). "RFC1 biallelic expansion is related to CANVAS, a rare genetic disorder characterized by cerebellar ataxia, sensory neuropathy/neuronopathy, and vestibular areflexia." (PMID 36555161, 2022).
Sensory neuropathy (continued). "Ultrasound was able to identify the one RFC1-positive participant who didn’t have a non-length-dependent sensory neuropathy; their only NCS abnormality was absent sural sensory responses (completely normal UL sensory responses)." (PMID 41322202, 2025). "While motor neuropathy is typically absent or minimal in RFC1-positive patients, 11 17 it co-occurred with sensory neuropathy in six of eight GAA-FGF14 patients." (PMID 37399286, 2024). "It is the prominence of the sensory neuropathy in CANVAS patients that led Currò and colleagues to investigate the possibility that the biallelic intronic RFC1 AAGGG repeat expansion might account for a proportion of people given a diagnosis of sporadic CIAP." (PMID 33983437, 2021). "RFC1 expansions were found in 34% of patients with sensory neuropathy, but in none with sensory-motor neuropathy." (PMID 33969391, 2021). "Biallelic RFC1 expansions were identified in 43 patients (34%) with sensory neuropathy and in none with sensory-motor neuropathy." (PMID 33969391, 2021). "Importantly, we have demonstrated that small nerves on ultrasound are a feature of RFC1-positive patients even when they have otherwise indistinguishable, length-dependent sensory neuropathy." (PMID 41322202, 2025). "Four of the five RFC1-positive patients satisfied the modified SNAP asymmetry score criteria for non-length-dependent sensory neuropathy;21 only one RFC1-negative patient had this combination of pure sensory findings and a positive modified SNAP asymmetry score." (PMID 41322202, 2025). "We confirm previous findings in similar, larger but less systematic studies that the absence of motor involvement, presence of chronic cough, and a non-length-dependent sensory neuropathy pattern are more common amongst patients with pathological RFC1 expansions." (PMID 41322202, 2025). "Although larger prospective studies are needed to elucidate the full spectrum and the natural history of RFC1 spectrum disorders, data from our cohort support an ‘iceberg’ hypothesis, where full CANVAS represents the tip, whereas isolated sensory neuropathy the bulk of the iceberg." (PMID 33969391, 2021). "To identify the symptoms and signs predictive of positive RFC1 testing, we compared 43 cases with sensory neuropathy and biallelic AAGGG expansions with 58 cases also diagnosed with sensory neuropathy but negative for AAGGG repeat expansions." (PMID 33969391, 2021).
Friedreich ataxia (16 papers, 2019 to 2025). An inherited condition that affects the nervous system and causes movement problems. "However, both CANVAS and Friedreich ataxia (FRDA) are caused by biallelic STR expansions in RFC1 and FXN respectively, and reflect two of the most common causes of AR HCAs." (PMID 38760634, 2024). "Compared to the total number of patients in our cohort (autosomal dominant and recessive), SCA27B accounted for 17%, Friedreich’s ataxia for 8%, and RFC1-CANVAS for 4%." (PMID 39227614, 2024). "In European natives, pathogenic mutations should be searched in genes producing SCA1 (ATXN1), SCA2 (ATXN2), SCA3 (ATXN3), SCA6 (CACNA1A), SCA7 (ATXN7), SCA 12 (PPP2R2B), fragile X tremor ataxia syndrome (FMR1), SCA17 (TBP), CANVAS syndrome (RFC1), and Friedreich ataxia (FXN) [53﻿]." (PMID 35986227, 2023).
folate deficiency (8 papers, 2015 to 2025). A nutritional condition produced by a deficiency of FOLIC ACID in the diet. "Increased expression of RFC-1 and PCFT has been reported during folate deficiency, whereas folate over-supplementation leads to downregulation of intestinal folate uptake via decreased transcription of RFC-1 and PCFT." (PMID 39998667, 2025). "While folate deficiency resulted in retinal vasculopathy, the expression and the role of RFC1 in blood-retinal barrier (BRB) are not well known." (PMID 37328777, 2023). "Several previous studies have shown that folate deficiency results in a significant upregulation of folate transport genes such as SLC19A1/RFC-1 and SLC46A1/PCFT." (PMID 30269276, 2018). "We found a relationship between RFC-1 polymorphisms and hyperhomocysteinemia and folate deficiency in individuals with ischemic stroke as well as some heterozygous and mutant homozygous SBI groups." (PMID 25659099, 2015). "During folate deficiency, an increased expression of RFC-1 and PCFT transporters has been reported." (PMID 36612253, 2022). "In addition, we found a relationship between RFC-1 polymorphisms and hyperhomocysteinemia and folate deficiency." (PMID 25659099, 2015). "In addition to its role in folate uptake, RFC-1 plays a critical role in folate homeostasis in mammalian cells, where it is down-regulated in response to folate deficiency." (PMID 25659099, 2015). "Therefore, inhibition of RFC-1 by salicylate at the level of blood brain barrier may result in cerebral folate deficiency, leading to cognitive impairment." (PMID 34866142, 2021). "Folic acid deficiency, MTHFD1 rs2236225, MTHFR rs1801133, MTRR rs1801349 and RFC1 rs1051226 polymorphisms may be maternal risk factors of NTDs." (PMID 30867013, 2019). "A similar transcriptional response has been previously observed in a mouse model of genetic folate deficiency-based NTD, the Reduced Folate Carrier 1 (RFC1) KO mouse, suggesting that this may be an adaptive mechanism to cope with an inadequate nutrient supply." (PMID 30290792, 2018).
Parkinson disease (7 papers, 2022 to 2026). A progressive degenerative disorder of the central nervous system characterized by loss of dopamine producing neurons in the substantia nigra and the presence of Lewy bodies in the substantia nigra and locus coeruleus. "Meanwhile, incomplete CANVAS phenotypes and a variety of additional, atypical symptoms such as autonomic dysfunction, bradykinesia, parkinsonism or dystonia expanded the phenotype of patients carrying pathogenic repeat expansions, which led to the terminology of RFC1 spectrum disorder." (PMID 38916676, 2024). "Interestingly, biallelic repeat expansions in RFC1 have also been associated with several other distinct neurodegenerative disorders, such as Parkinson’s disease and atypical parkinsonism such as multiple system atrophy (MSA)." (PMID 38916676, 2024). "Three had already been tested for RFC1; four were excluded due to diagnoses of Parkinson’s disease, alcoholism and bilateral amputations." (PMID 41322202, 2025). "Here we report on screening of a population-based cohort of Finnish patients with medicated parkinsonism for RFC1 (AAGGG)exp." (PMID 35013364, 2022). "We present a patient with CANVAS and biallelic RFC1 expansions who developed Parkinsonism with severe autonomic involvement similar to that seen in classical MSA." (PMID 36177974, 2022). "The expansion in RFC1 has also been found in occasional patients with MSA, in a patient with CANVAS and levodopa responsive parkinsonism and in a patient with features of Lewy body dementia." (PMID 35013364, 2022).
hereditary ataxia (6 papers, 2021 to 2026). An instance of an atactic disorder that is caused by an inherited genomic modification in an individual. "The pentanucleotide repeat expansion in RFC1 is a frequent cause of polyneuropathy as well suggesting that routine diagnostic testing should be carried out in patients with suspected hereditary ataxia or polyneuropathy." (PMID 34600502, 2021). "In case no RFC1 repeat expansion can be detected, further genetic testing is recommended, since some hereditary ataxias may present with a CANVAS-like phenotype – particularly, SCA3 and FRDA." (PMID 38835435, 2021).
osteosarcoma (5 papers, 2019 to 2024). A usually aggressive malignant bone-forming mesenchymal neoplasm, predominantly affecting adolescents and young adults. "The significant correlation between low RFC1 mRNA expression at diagnosis, poor histological response, and osteosarcoma recurrence warrants larger-scale investigation." (PMID 39335211, 2024). "In our osteosarcomas, the expression of RFC1 negatively predicted the chemotherapeutic response." (PMID 39335211, 2024). "Contrary to drug efflux, the Replication Factor C Subunit 1 (RFC1 gene), situated on the tumour cell membrane, modulates the accumulation of methotrexate (MTX), a chemotherapeutic agent commonly used in osteosarcomas." (PMID 39335211, 2024).
breast carcinoma (4 papers, 2016 to 2023). "A recent prospective case-control study reported that RFC1 80G>A is associated with LINE-1 undermethylation as measured in peripheral blood DNA of women who developed breast cancer as compared with breast cancer-free controls." (PMID 27936032, 2016). "We investigated whether GSTT1 (“null” allele), GSTM1 (“null”allele), GSTP1 (A313G), RFC1 (G80A), MTHFR (C677T), TS (2R/3R) polymorphisms were associated with toxicity and survival in patients with early breast cancer (EBC) treated with adjuvant chemotherapy (CT)." (PMID 28747156, 2017). "Instead of directing flows with cell cycle regulators as in the case of breast cancer, there are in general uncoordinated functions between RB1 with transcriptional regulators LMO2 and PML and RFC1 that regulate DNA replication." (PMID 26975659, 2016).
multiple system atrophy (4 papers, 2021 to 2024). Multiple system atrophy (MSA) is a neurodegenerative disorder characterized by autonomic failure (cardiovascular and/or urinary), parkinsonism, cerebellar impairment and corticospinal signs with a median survival of 6-9 years. "Besides, increasing evidence has also suggested a linkage between the RFC1 AAGGG repeat expansion and several other neurodegenerative diseases including the Parkinson's disease (PD), multiple system atrophy (MSA) and chronic idiopathic axonal polyneuropathy (CIAP)." (PMID 38266156, 2024).
polyneuropathy (4 papers, 2021 to 2024). A disease or disorder affecting more than one nerve. "Third, we were unable to objectify the presence of polyneuropathy—a universal feature of RFC1-related disorder —in all RFC1-positive patients as only 40% underwent NCS." (PMID 38381176, 2024). "Polyneuropathy was identified in 12 of 15 (80%) RFC1-positive patients, and was diagnosed on NCS in six patients and clinically in six patients." (PMID 38381176, 2024). "The DBN syndrome in RFC1-positive patients was characterized by additional cerebellar impairment in 100% (15/15), bilateral vestibulopathy (BVP) in 100% (15/15), and polyneuropathy in 80% (12/15) of cases." (PMID 38381176, 2024). "The frequency of biallelic RFC1 repeat expansions stratified by DBN subgroups was 50% (3/6) for DBN plus cerebellar impairment and BVP, and 86% (12/14) for DBN plus cerebellar impairment, BVP, and polyneuropathy." (PMID 38381176, 2024).
sensory ataxia (4 papers, 2021 to 2025). Any ataxia in which the causes of the disease is a perturbation of the sensory system, leading to its dysfunction. "The high diagnostic rate of sensory ataxia subgroup was driven by the detection of RFC1 homozygous repeat expansion." (PMID 40488180, 2025). "Gait ataxia with clinical evidence of sensory ataxia, that is, marked worsening without visual control (98%) or a positive Romberg test (93%), was the main feature of RFC1 disease." (PMID 33495376, 2021).
acute lymphoblastic leukemia (3 papers, 2013 to 2016). Leukemia with an acute onset, characterized by the presence of lymphoblasts in the bone marrow and the peripheral blood. "The characteristics of the included studies on RFC1 G80A polymorphism acute lymphoblast leukemia risk." (PMID 27222703, 2016). "The RFC1 80AA genotype was also associated with increased risk for acute lymphoid leukaemia with worse outcome, higher chance of relapse and poorer survival as compared to GA and GG genotypes." (PMID 27936032, 2016). "The mutation G80A in RFC-1 has been associated with post-methotrexate treatment survival of children with acute lymphoblastic leukemia." (PMID 23733889, 2013). "Increasing studies have been conducted on the association of RFC1 G80A polymorphism with acute lymphoblastic leukemia (ALL) risk." (PMID 27222703, 2016).
amyotrophic lateral sclerosis (3 papers, 2022 to 2024). Amyotrophic lateral sclerosis (ALS) is a neurodegenerative disease characterized by progressive muscular paralysis reflecting degeneration of motor neurons in the primary motor cortex, corticospinal tracts, brainstem and spinal cord. "Intron 2 retention in RFC1 pre-mRNA across various tissues has been identified in patients, which is known as a common event associated with other disease-causing guanine-cytosine-rich intronic expansions, like myotonic dystrophy type 2 and C9orf72-amyotrophic lateral sclerosis." (PMID 36061987, 2022).
colorectal cancer (3 papers, 2013 to 2024). A primary or metastatic malignant neoplasm that affects the colon or rectum. "The higher frequency of OAT2 and RFC1 expression in colorectal cancer specimens, compared to the corresponding normal tissues, may indicate that an increased expression of OAT2 and RFC1 is associated with the development of colorectal cancer." (PMID 24649225, 2013). "In colorectal cancer tissues, the staining levels of RFC1, RFC2, RFC4, and RFC5 protein expression were modest." (PMID 38504096, 2024). "High expression levels of OAT2 and RFC1 were observed in 40 and 29% of pre-treated colorectal cancer specimens, respectively, whereas the corresponding normal colorectal epithelia were negative or weakly positive for the two transporters." (PMID 24649225, 2013). "It is suggested that the expression of OAT2 and RFC1 in tumor cells may be of predictive value for the effectiveness of UFT/LV chemotherapy in colorectal cancer patients." (PMID 24649225, 2013). "Immunohistochemical analysis of OAT2 and RFC1 expression may be a useful tool to identify colorectal cancer patients who may benefit from treatment with an UFT/LV regimen." (PMID 24649225, 2013). "However, our findings were based on a retrospective analysis of a limited patient sample; thus, a large-scale prospective trial is required to confirm OAT2 and RFC1 expression as prognostic indicators in colorectal cancer patients receiving oral UFT/LV chemotherapy in the adjuvant setting." (PMID 24649225, 2013). "Therefore, immunohistochemical analysis of OAT2 and RFC1 may serve as a useful tool for predicting the efficacy of UFT/LV treatment regimens in colorectal cancer patients." (PMID 24649225, 2013). "Given that RFC1 and RFC5 exhibited intensity levels greater than 75%, they emerged as more promising biomarkers for colorectal cancer development." (PMID 38504096, 2024).
Cough (3 papers, 2020 to 2025). A sudden, audible expulsion of air from the lungs through a partially closed glottis, preceded by inhalation. "Chronic cough was the only feature on history or exam present in all five RFC1-positive participants, compared with four of the 38 RFC1-negative participants (P = 0.0002)." (PMID 41322202, 2025).